TRAPPC1 (trafficking protein particle complex subunit 1)
Description:
May play a role in vesicular transport from endoplasmic reticulum to Golgi.
Synonyms: BET5; MUM2
Tractability: Antibody: its Gene Ontology location is reachable by antibodies, with high confidence. PROTAC: ubiquitination databases record sites on it; its protein half-life has been measured.
Gene: Protein-coding gene on chromosome 17 (7,930,345 to 7,932,123, reverse strand). Ensembl gene ENSG00000170043.
Subcellular location: Golgi apparatus, cis-Golgi network; Endoplasmic reticulum
Pathways (Reactome):
Vesicle-mediated transport: COPII-mediated vesicle transport; RAB GEFs exchange GTP for GDP on RABs
Immune System: Neutrophil degranulation
Gene Ontology:
Molecular function: protein binding
Biological process: COPII vesicle coating; endoplasmic reticulum to Golgi vesicle-mediated transport; vesicle coating; vesicle-mediated transport
Cellular component: azurophil granule lumen; cytoplasm; cytosol; extracellular region; TRAPP complex; TRAPPII protein complex; TRAPPIII protein complex; endoplasmic reticulum; Golgi apparatus
Genetic constraint (gnomAD): Loss-of-function variants: 10 observed, 18.26 expected, observed/expected ratio (o/e) 0.55, 90% interval 0.34 to 0.93. The upper end of that interval is the gene's LOEUF score, 0.93, which puts it in group 3 of 6, group 1 being the genes least tolerant of losing a copy. Missense variants: 163 observed, 195.99 expected, observed/expected ratio (o/e) 0.83, 90% interval 0.73 to 0.95. Synonymous variants: 85 observed, 80.14 expected, observed/expected ratio (o/e) 1.06, 90% interval 0.89 to 1.27.
Homologues: Orthologues: chimpanzee TRAPPC1 (100% identical), dog TRAPPC1 (100% identical), macaque TRAPPC1 (100% identical), rabbit TRAPPC1 (100% identical), mouse Trappc1 (99% identical), rat Trappc1 (99% identical), guinea pig TRAPPC1 (98% identical), zebrafish trappc1 (79% identical), tropical clawed frog trappc1 (75% identical), Drosophila melanogaster Bet5 (54% identical), Caenorhabditis elegans trpp-1 (38% identical). Paralogues in human: TRAPPC4 (28% identical).
Diseases named in the same sentence as TRAPPC1 in open-access papers:
TRAPPC1 is named in the same sentence as 5 diseases in open-access papers, as found by Europe PMC text mining. Sharing a sentence is not in itself a finding about the gene and the disease. The quoted sentences say what the papers report.
melanoma (1 paper, 2007). A malignant, usually aggressive tumor composed of atypical, neoplastic melanocytes. "For example, a missense mutation in human Bet5/TRAPPC1 results in the expression of antigenic peptides in melanoma; and the SEDL/Trs20 gene is responsible for SEDT, an Xlinked skeletal disorder." (PMID 17274825, 2007).
cancer (2 papers, 2016 to 2022). A tumor composed of atypical neoplastic, often pleomorphic cells that invade other tissues. "For example, to date four TRAPP subunits are implicated in cancer: TrappC1 (Bet5), TrappC4 (Trs23), TrappC9, and TrappC10." (PMID 27066478, 2016). "The eight cross-cancer CpGs were annotated to genes involved in transport (KCNA3, KCNAB3 and TRAPPC1), signal transduction (AGAP3 and LIME1), microtubule assembly (FES and SHROOM1), and metal binding (FURIN and AGAP3)." (PMID 35710732, 2022).
infection (2 papers, 2022 to 2025). The state of being infected such as from the introduction of a foreign agent such as serum, vaccine, antigenic substance or organism. "Furthermore, there were nine proteins that were specifically detected at 7 days post-infection (Saa2, Trappc1, Cxadr, Armc8, Hbxip; Lamtor5, Prppsap2, Usp46, Pcdh10, Neo1)." (PMID 36061859, 2022).
myopathy (1 paper, 2024). A disease of the muscle in which the muscle fibers do not function properly. "This system was used for studying the first reported individual with an autosomal recessive disorder caused by biallelic TRAPPC1 variants, a girl with a severe neurodevelopmental disorder and myopathy." (PMID 39273027, 2024).
TRAPPC1 also shares sentences with these, for which no sentence is quoted: neurodevelopmental disorder (1 paper).